GOT1 (glutamic-oxaloacetic transaminase 1)
Diseases named in the same sentence as GOT1 in open-access papers (continued):
Sharing a sentence is not in itself a finding about the gene and the disease.
pancreatic ductal adenocarcinoma (18 papers, 2015 to 2024). An infiltrating adenocarcinoma that arises from the epithelial cells of the pancreas. "Oncogenic KRAS activates GOT1/2 to promote glutamine metabolism, which supports aspartate production in pancreatic ductal adenocarcinoma (PDAC) cells." (PMID 37488138, 2023). "GOT1 contributes to cancer cell proliferation, migration, and invasion in pancreatic ductal adenocarcinoma and colorectal cancer." (PMID 36387145, 2022). "In recent years, the GOT1 metabolic pathway has been found to play an important role in many cancers, such as glioblastoma multiforme, small cell lung cancer, pancreatic ductal adenocarcinoma (PDCA), and BC." (PMID 35978348, 2022). "In pancreatic ductal carcinoma, GOT1 knockdown abolished glycolysis, nucleotide metabolism and redox homeostasis, which inhibited tumor growth, while this was not seen in CRC." (PMID 34590603, 2021). "Human pancreatic ductal adenocarcinoma (PDAC) relies on the pathway involving GOT1 and knockdown of it is shown to increase reactive oxygen species and a decrease in growth." (PMID 32249812, 2020). "A study demonstrated that one of the mechanisms of KRAS in inducing pancreatic ductal adenocarcinoma is by up-regulating GOT1 and inhibiting glutamate dehydrogenase 1 (GLUD1), thus reprogramming glutamine metabolism." (PMID 32266153, 2020). "We have previously shown that central carbon metabolism is rewired in pancreatic ductal adenocarcinoma (PDA) to support proliferation through a glutamate oxaloacetate transaminase 1 (GOT1)-dependent pathway." (PMID 31908776, 2020). "Specifically, pancreatic ductal adenocarcinoma (PDAC) cells rely on an unconventional metabolic pathway catalyzed by aspartate transaminase 1 (GOT1) to rewire glutamine metabolism and support nicotinamide adenine dinucleotide phosphate (NADPH) production." (PMID 31470862, 2019). "We propose the GOT1 expression status as a simple and reliable prognostic biomarker in pancreatic ductal adenocarcinoma." (PMID 25595905, 2015). "In summary, we report the GOT1 tumor tissue status as an independent prognostic biomarker in pancreatic ductal adenocarcinoma." (PMID 25595905, 2015). "In addition, the proliferation of PDAC cells is also inhibited upon selective inhibition of GOT1 expression in tumor cells, and these phenomena suggest that targeting GOT1 may be a novel approach for the treatment of pancreatic ductal carcinoma." (PMID 36497150, 2022). "In pancreatic ductal adenocarcinoma cells (PDAC), the downregulation of Sirt5 or its knock-down led to an increase in the activity of glutamate oxaloacetate transaminase 1 (GOT1) through acetylation." (PMID 38605962, 2024). "In pancreatic ductal adenocarcinoma (PDAC), GOT1 is required to sustain cell growth by enabling the production of NADPH to compensate for internal ROS33." (PMID 32111915, 2020). "In pancreatic ductal adenocarcinoma (PDAC) cells, glutamine-derived aspartate was shown to be converted to OAA by GOT1 and GOT1 was also involved in the maintenance of the redox homeostasis through the sequential conversion of OAA into pyruvate." (PMID 29751795, 2018). "In pancreatic ductal adenocarcinoma (PDAC) cells, for example, SIRT5 catalyzes the deacetylation of aspartate transaminase 1 (GOT1) at specific lysine residues, thereby inhibiting its enzymatic activity and suppressing the glutamine–glutathione metabolic pathway." (PMID 39201811, 2024).
melanoma (17 papers, 2018 to 2024). A malignant, usually aggressive tumor composed of atypical, neoplastic melanocytes. "Overexpression of miR-9, also down- regulated the expression of glutamic-oxaloacetic transaminase 1 (GOT1) in melanoma, decreased lipid peroxidation, and iron accumulation, causing cells to escape from ferroptosis." (PMID 37996827, 2023). "For instance, in melanoma, miR-9 targeted GOT1 directly, inhibiting the expression of GOT1, which suppressed ferroptosis of melanoma cells." (PMID 39777342, 2024). "miR-9 regulates ferroptosis by targeting glutamate oxaloacetate transaminase 1 (GOT1), then reduce ROS levels in melanoma cells." (PMID 35688814, 2022). "miR-9 binds to GOT1 3’UTR mRNA in melanoma cells, with a subsequent reduction in ferroptosis induced by Erastin and RAS-selective lethal (RSL3)." (PMID 32326003, 2020). "Furthermore, in melanoma cells, miR-9 regulates ferroptosis by directly inhibiting glutamic oxaloacetic transaminase 1 (GOT1), which plays a critical role in amino acid metabolism, particularly in the metabolism of glutamine, a key factor in ferroptosis." (PMID 39595619, 2024). "Moreover, GOT1 downregulation suppressed ferroptosis in melanoma by reducing α-ketoglutarate which is a metabolic intermediate in ROS production." (PMID 36733386, 2022). "As reported, miR-9 regulates ferroptosis by targeting GOT1 in melanoma." (PMID 35038133, 2022). "In melanoma cells, miR-9 is able to inhibit catalytic efficacy of glutamic-oxaloacetic transaminase 1 (GOT1) and halt transamination of a-ketoglutarate (a-KG), while inhibition of miR-9 causes accumulation of lipid ROS, and eventually exacerbates the enforcement of ferroptosis." (PMID 34235152, 2021). "For example, miR-9 could reduce erastin- and RSL3-induced ferroptosis via repressing glutamate oxaloacetate transaminase 1 (GOT1) in melanoma, and this effect could be rescued by inhibiting the glutaminolysis process." (PMID 34611144, 2021). "In melanoma cell lines G-361 and A375, miR-9 can inhibit ferroptosis via targeting glutamic-oxaloacetic transaminase 1 (GOT1), an enzyme via glutaminolysis converting glutamine (Gln) ultimately to α-ketoglutarate (α-KG), which can promote ROS accumulation and thus irritate ferroptosis." (PMID 30925886, 2019). "Interestingly, the GOT1 level was significantly higher in metastatic melanoma than primary melanoma tissues." (PMID 29751795, 2018). "Finally, analysis of a sequencing dataset and mRNA expression datasets showed that increased GOT1 expression is found in lung adenocarcinoma and melanoma." (PMID 29751795, 2018). "For instance, inhibition of miR-137 and miR-9 enhanced RSL3-induced ferroptosis in melanoma by targeting SLC5A1 and GOT1, respectively, in the glutamine metabolism pathway." (PMID 37626043, 2023).
breast carcinoma (10 papers, 2015 to 2024). "High levels of GOT1 were further linked to poor survival as analysed by the GEPIA web tool, in thyroid and breast carcinoma and in lung adenocarcinoma." (PMID 29751795, 2018). "Additionally, targeting metabolic vulnerability to block of transamination of GOT1 using AOA suppressed the growth of breast cancer cells in a TAZ/YAP-dependent manner." (PMID 39777342, 2024). "TAZ/YAP can induce the expression of glutamate oxaloacetate transaminase 1 (GOT1) and PSAT1 to produce more α-ketoglutarate and to promote the growth of breast cancer cells." (PMID 37147729, 2023). "QPCR analysis performed at two different time points, 48h and 72h, indicated an up-regulation of Slc1a5, GOT1 and IDH1 at 72h in FSK treated samples, hence confirming also in human breast cancer cells a role of PKA activation in glutamine metabolism." (PMID 26978032, 2016). "TAZ/YAP reprogram cellular energetics to promote the dependence of breast cancer cell growth on exogenous Gln, and TAZ/YAP induced GOT1 and phosphoserine aminotransferase (PSAT1) expression to promote the conversion of Gln to α-KG, and then to support cell growth." (PMID 39777342, 2024). "The expression of GOT1 was up-regulated in pancreatic ductal adenocarcinoma (PDAC), colorectal cancer, breast cancer, lung adenocarcinoma, glioblastoma, prostate cancer, acute myeloid leukemia, and multiple myeloma, while down-regulated in poorly-differentiated hepatocellular carcinoma cells." (PMID 39777342, 2024). "GOT1 - the aspartate transaminase induced by YAP/TAZ, confers glutamine dependency to breast cancer cells and targeting this metabolic vulnerability using aminooxyacetate (AOA) represses breast cancer cell proliferation." (PMID 32206112, 2020). "Inhibition of GOT1 could regulate NADPH synthesis and then regulated ROS levels to counteract oxidative stress, which making colorectal cancer cells sensitive to 5-fluorouracil and breast cancer cells sensitive to doxorubicin, enhancing anti-cancer effects." (PMID 39777342, 2024).
colorectal cancer (9 papers, 2018 to 2025). A primary or metastatic malignant neoplasm that affects the colon or rectum. "It has been shown that KL-11743 synergizes with mutations in GOT1, a glutamate oxaloacetate transaminase used in the shuttle, in a colorectal carcinoma cell line." (PMID 39863913, 2025). "Meanwhile, GOT1 overexpression reduces the sensitivity of colorectal cancer cells to 5-fluorouracil (5-FU) and triple-negative breast cancer cells to doxorubicin." (PMID 36387145, 2022). "Differential expression levels of GOT1 have been reported in several cancers including breast, lungs, brain, and colorectal cancer." (PMID 32322560, 2020). "Through further analysis of GOT1 with the Oncomine database, we found the GOT1 gene expression levels to vary in different types of cancers, for instance the GOT1 expression was up-regulated in breast and lung cancer, while down-regulated in brain and colorectal cancer." (PMID 29751795, 2018). "We utilized a doxycycline-inducible shRNA-mediated strategy to knockdown GOT1 in PDA and colorectal cancer (CRC) cell lines and tumor models of similar genotype." (PMID 31908776, 2020). "The present study identified six hub targets—GOT1, CYP2C9, CYP34, CYP1A2, CA2, and ABAT—that are involved in five core pathways related to HQD’s effects on malignant progression in colorectal cancer liver metastases, integrating transcriptomic and metabolomic analyses." (PMID 40732339, 2025).
Sepsis (7 papers, 2022 to 2025). Sepsis is defined as life-threatening organ dysfunction caused by a dysregulated host response to infection. "In the present study, we concluded that miR-9-5p regulates sepsis-induced ferroptosis by targeting GOT1, thus causing SAE." (PMID 35038133, 2022). "We found that exosomal NEAT1 transported into the cerebral cortex and functions as a ceRNA for miR-9-5p to facilitate TFRC and GOT1 expression, therefore, play important roles in sepsis-induced ferroptosis and SAE." (PMID 35038133, 2022). "We investigate the ceRNA axis NEAT1/miR-9-5p/TFRC/GOT1 on sepsis-induced ferroptosis for the first time in the present study." (PMID 35038133, 2022). "Taken together, the result revealed that miR-9-5p, sponged by NEAT1, targeted TFRC and GOT1 that overexpressed in vitro and in vivo and might promote sepsis-induced ferroptosis in brain microvascular endothelial cells." (PMID 35038133, 2022). "miR-9-5p alleviates sepsis-induced ferroptosis by inhibiting the expression of TFRC and GOT1 in vivo." (PMID 37008225, 2023). "The present study provided a clue for SAE of sepsis-induced ferroptosis through axis NEAT1/miR-9-5p/TFRC and GOT1." (PMID 35038133, 2022). "In the present study, we found that miR-9-5p alleviated sepsis-induced neurons ferroptosis by suppressing the expression of TFRC and GOT1." (PMID 35038133, 2022). "Increased miR-9-5p alleviated sepsis-induced ferroptosis by suppressing the expression of TFRC and GOT1 both in vivo and in vitro." (PMID 35038133, 2022). "Sepsis induced high expression of serous exosome-derived NEAT1, which might exacerbate SAE by regulating the miR-9-5p/TFRC and GOT1 axis to promote siderosis." (PMID 37008225, 2023). "The present study aimed to figure out whether exosomal lncRNA NEAT1 affects sepsis-induced ferroptosis through NEAT1/miR-9-5p/TFRC and GOT1 axis." (PMID 35038133, 2022). "In conclusion, these findings suggest that sepsis induced high expression of serous exosome-derived NEAT1, and it might exacerbate SAE by promoting ferroptosis through regulating miR-9-5p/TFRC and GOT1 axis." (PMID 35038133, 2022). "on sepsis-inducing plasmacytoid exosome-derived lncRNANEAT1 suggest that it may promote ferroptosis by modulating the miR-9-5p/transferrin receptor (TFRC) and glutamic-oxaloacetic transaminase 1 (GOT1) axes, ultimately exacerbating SAE." (PMID 35990689, 2022).
glioblastoma (6 papers, 2018 to 2024). The most malignant astrocytic tumor (WHO grade IV). "GOT1 inhibited glycolysis by interacting with pyruvate carboxylase and then inhibited malignant phenotypes of glioblastoma multiforme cells." (PMID 39777342, 2024). "GOT1 can inhibit the malignant phenotype of glioblastoma cells by interacting with PC and inhibiting glycolysis." (PMID 36499136, 2022). "GOT1 is rarely expressed in glioblastoma, and cancer patients with a high expression of GOT1 have a better prognosis." (PMID 36499136, 2022).
ovarian carcinoma (5 papers, 2022 to 2024). A malignant neoplasm originating from the surface ovarian epithelium. "GOT1 modulates cellular metabolism by coordinating the use of carbohydrates and amino acids to satisfy dietary needs for long-term proliferation; in ovarian cancer, adapalene suppresses the growth of ovarian cancer cells by binding to GOT1." (PMID 38178187, 2024). "ADA has been shown to induce cell death in hepatoma cells by regulating the ratio of BAX and BCL-2, to impede proliferation in ovarian cancer via GOT1 inhibition, and to exert pronounced anti-cancer activity in prostate cancer cells by inducing DNA damage, cell cycle arrest and apoptosis." (PMID 39175546, 2024). "Adapalene, an approved drug clinically used in the therapy of acne vulgaris, could selectively inhibit the activity of GOT1 in a non-competitive manner and further suppress the proliferation of ovarian cancer ES-2 cells." (PMID 39777342, 2024).
acute myeloid leukemia (4 papers, 2018 to 2022). Acute myeloid leukemia (AML) is a group of neoplasms arising from precursor cells committed to the myeloid cell-line differentiation. "In acute myeloid leukemia, upregulation of GOT1 was also found to be associated with a worse prognosis." (PMID 34590603, 2021). "An increased GOT1 expression predicts an adverse prognosis in acute myeloid leukemia." (PMID 36387145, 2022).
Cerebral ischemia (4 papers, 2020 to 2025). Restriction of arterial blood supply to the brain associated with insufficient oxygenation to support the metabolic requirements of the tissue. "CSF GOT1 was significantly higher in patients with uncontrolled intracranial hypertension and cerebral ischemia post-SAH, and independently predicted poor neurological outcomes." (PMID 37002262, 2023). "Additionally, GOT1 treatment reduced serum Glu concentration, and GOT1-induced protective effects in cerebral ischemia were mediated by Asp metabolism." (PMID 39777342, 2024). "Meanwhile, Medioresinol (MDN) promoted Phe metabolism by increasing the expression of GOT1 and PAH after cerebral ischemia, and inhibited the apoptosis of cerebral microvascular endothelial cells." (PMID 40248014, 2025). "GOT1 activity in SAH participants was significantly higher in patients with increased ICP and cerebral ischemia, indicating early enzyme involvement in the neuropathology of SAH patients." (PMID 37002262, 2023). "GOT1, which was upregulated in the miR-146a KO microglia, is a transaminase enzyme, which has previously been shown to be neuroprotective in animal models of amyotrophic lateral sclerosis (ALS) and cerebral ischemia, regulating the level of extracellular glutamate." (PMID 32582192, 2020). "Importantly, we found that serum glutamate level and CSF GOT1 activity during the first week after SAH were significantly higher in patients with the presence of cerebral ischemia on later CT scan compared to those without cerebral ischemia, and were independent predictors of elevated ICP." (PMID 37002262, 2023).
glioma (4 papers, 2021 to 2025). A benign or malignant brain and spinal cord tumor that arises from glial cells (astrocytes, oligodendrocytes, ependymal cells). "The results implied that advanced age, high-grade tumor, 1p/19q non-codeletion, IDH-non mutation, low expression of ATP6V1G2, GABARAPL1 and GOT1 might be poor prognostic factors for glioma patients." (PMID 35896732, 2022). "Silencing HIF-1α with siRNA in the G55 glioma cell line reversed this hypoxia-induced suppression of GOT1 and GOT2 expression." (PMID 39914740, 2025). "Overall, the expression of ATP6V1G2, GABARAPL1 and GOT1 was significantly elevated in low-grade glioma compared to high-grade glioma." (PMID 35896732, 2022). "The expression of ATP6V1G2, GABARAPL1, GOT1 along with common glioma characteristics (age, gender, race, tumor grade, 1p/19q status, IDH status) were included in the univariate Cox regression analysis." (PMID 35896732, 2022). "Combined with their high expression in non-glioma samples, we speculated that ATP6V1G2, GABARAPL1, and GOT1 might be suppressor genes for glioma." (PMID 35896732, 2022). "Also, K–M curves in 313 gliomas sample through CGGA database showed that low expression of ATP6V1G2, GABARAPL1 and GOT1 was associated with poor prognosis, which was consistent with the results from the TCGA database." (PMID 35896732, 2022). "The authors examined how hypoxia-induced stabilization of HIF-1α affects the expression of GOT1 and GOT2 in G55 human glioma cells, which possess the VHL protein and lack constitutive HIF-1α activation." (PMID 39914740, 2025).
hepatocellular carcinoma (4 papers, 2014 to 2024). A malignant tumor that arises from hepatocytes. "The nuclear receptor liver receptor homolog 1 (LRH-1) (also known as NR5A2) was recently found to have a regulatory role in hepatoma formation, since it was shown to upregulate mitochondrial ALT2/GPT2 and cytosolic AST1/GOT1 aminotransferase isoforms as well as glutaminase 2 (GLS2)." (PMID 30416487, 2018).
lung carcinoma (4 papers, 2014 to 2023). "The analysis of overall survival rate also indicated that a high level of GOT1 expression was linked to poor survival rate in certain types of tumors, including thyroid carcinoma, breast invasive carcinoma and lung cancer." (PMID 29751795, 2018). "X Zhou in 2018 demonstrated that in GOT1-null 143B osteosarcoma cells or GOT1 siRNA knockdown in A549 lung cancer cells resulted in the elevated expression of autophagy-related genes (ATG5 and Beclin1) and increased secretion rate of lactate compared with wild type cells." (PMID 37190124, 2023).
prostate carcinoma (4 papers, 2020 to 2024). A carcinoma that arises from epithelial cells of the prostate gland. "Prostate cancers appear to undergo GOT1-dependent metabolic adaptation to promote a malignant phenotype and resist oxidative stress." (PMID 32111915, 2020). "Both LNCaP and PC3 cells showed increased ROS levels upon GOT1 knockdown, suggesting that GOT1 plays a role in cellular redox balance and can be manipulated to reduce the viability of prostate cancer cells." (PMID 32111915, 2020). "To investigate GOT1’s role as a regulatory metabolic node in prostate cancer, we knocked down GOT1 in the prostate cancer cell lines LNCaP and PC3 using siRNA." (PMID 32111915, 2020). "We therefore examined the mechanism by which GOT1 regulated prostate cancer cell viability." (PMID 32111915, 2020). "Additionally, knockdown of GOT1 decreased NADPH production and suppressed prostate cancer cell growth." (PMID 39777342, 2024). "Furthermore, we identified aberrant levels of glutamate, the product of GOT1, in primary and metastatic prostate cancers compared to normal." (PMID 32111915, 2020).